BRCA1 (BRCA1 DNA repair associated)
Diseases named in the same sentence as BRCA1 in open-access papers (continued):
Sharing a sentence is not in itself a finding about the gene and the disease.
tumor (continued). "In August 2018, Ontario became the first Canadian province to implement reflex BRCA1/2 tumour genetic testing for all newly diagnosed HGOSC patients." (PMID 35418215, 2022). "The high expression of UHRF1 inhibits a variety of tumor suppressor genes, such as BRCA1, KISS1, and MEG." (PMID 35656341, 2022). "The secretory cells of BRCA1+ samples had differentially expressed genes involved in tumor growth and regulation, chemokine signaling, and antigen presentation compared to the wild-type BRCA1 controls." (PMID 36076202, 2022). "Regarding the first aspect, potentially the Tumor-First workflow will contribute to more frequent and earlier knowledge of a hereditary BRCA1/2-PV within a family." (PMID 34997316, 2022). "In this single-center study, we report BRCA1/2 mutational status, HRD score and signature 3 levels, all obtained by tumor exome sequencing, in 86 patients with various subtypes of MBC and who received platinum-based chemotherapy." (PMID 35246547, 2022). "Germline and tumour BRCA1/2 status are highly concordant (i.e., most tBRCAmut alterations are germline), although BRCA1/2 mutations detected in 5%─7% patients with HGSOC are identified in the tumour, but not through germline testing." (PMID 35781107, 2022). "Elevated HMMR in mouse mammary epithelium enhances the rate of Brca1-mutant carcinogenesis as it is involved in modifying the phenotype of tumor cell and tumor microenvironment." (PMID 36199789, 2022). "The upregulation of BRCA1 in IS was related to tumor promotion, platelet activation, and angiogenesis." (PMID 36118697, 2022). "BRCA1 and BRCA2 genes encode proteins that help maintain genomic stability and act as tumour suppressors." (PMID 35444210, 2022). "Consistent with above analysis, the S100A9 peptides were identified in all five groups and the number of identified S100A9 peptides were coordinately increased with tumor development stages in Brca1-MT mouse mammary tissues." (PMID 35304461, 2022). "We noticed that the majority of Tgfβr2 positive p18−/−;Brca1+/− tumor cells were co-stained with Ck14, indicative of the epithelium origin of the Tgfβr2 positive tumor cells." (PMID 35236825, 2022). "Regarding the relationship between iNOS/NO and BRCA1, it was found that NO indirectly inhibits BRCA1 promoter activity, and NO can alter BRCA1 tumor suppressor activity." (PMID 35740092, 2022). "We found that ~21% (6/39) of BCBM cases had the presence of Breast K signature mutually exclusive to the other BCBM enriched mutational signatures, independently of somatic or germline BRCA1/2/PALPB2 mutations and tumor mutational burden." (PMID 35082299, 2022). "As expected, we found that the tumor epithelial areas in the PRAD specimens displaying strong staining of lamin B1 also had heavy signals of BRCA1." (PMID 35241075, 2022). "In OC, BRCA1 affects the migration of tumor cells by regulating CAPN1 and plays an important role in double-stranded DNA damage repair via its interaction with SIRT2." (PMID 35941978, 2022). "BRCA1 has been demonstrated to regulate de novo fatty acid synthesis, and protect tumor cells against oxidative stress." (PMID 36193432, 2022). "By incorporating MYC overexpression and Brca1 disruption into the platform, we substantially accelerate tumor onset and enable modeling of clinically important HR-deficient tumors." (PMID 35082152, 2022). "The TFs for cycling tumor cells mainly regulate the expression of genes required for progression through the cell cycle (e.g., BRCA1, E2F8), consistent with its proliferation phenotype." (PMID 35860547, 2022). "Reactivation of BRCA1/2 and/or other DDR-associated genes can result in tumour cells which are drug resistant and have functional DNA damage repair." (PMID 35326684, 2022). "Other truncating mutations of tumor related genes (APC, BRCA1, EGFR, FLT4, etc) were also decreased rapidly during treatment." (PMID 36341335, 2022).
tumor (continued). "For example, high expression levels of ERCC1 and BRCA1, which are crucial for DNA repair, negatively affect the efficacy of platinum drugs and are thought to be a major predictor of tumor responses to platinum-based chemotherapy." (PMID 36294786, 2022). "The receptor 1JNX is the C-terminal BRCT region of BRCA1 and is essential for DNA repair, tumor suppressor functions, and transcriptional regulation." (PMID 35966725, 2022). "USP1 was found to be up-regulated in BRCA1 mutant tumours where it appears to stabilise and protect the replication fork, thereby promoting survival in these cells with on-going DNA damage due to BRCA1 loss or mutation." (PMID 36240066, 2022). "One study shows that 45% of BRCA1-mutated tumours possess MYC amplification and that BRCA1 mutations are typical in TNBC." (PMID 35267409, 2022). "Patients with BRCA1/2 mutated tumors tended to have received platinum earlier in the disease course, without the difference being significant when compared with patients with BRCA1/2 WT tumor status (p = 0.12)." (PMID 35246547, 2022). "Patient 1 received RT to a left inguinal LN recurrence and achieved CR, then maintained with Olaparib (her tumor had BRCA1 deletion)." (PMID 36290878, 2022). "We have shown that NGS with a commercial kit for detection of BRCA1/2 mutants from FFPE tumor tissue is fully efficient." (PMID 35300046, 2022). "In the BRCA1-deficient mouse breast cancer model, DMXAA also promoted the polarization of macrophages to M1 in the tumor microenvironment, thus enhancing the anti-tumor activity of macrophages." (PMID 36545321, 2022). "Our search for a method capable of adjusting methylation estimates to account for tumor purity started with our observations in the BRCA1 gene locus." (PMID 36084090, 2022). "At this time, in Ontario, only BRCA1/2 testing is mandated for the determination of PARPi therapy eligibility, and as such, tumour testing cannot supplant germline testing." (PMID 36011309, 2022). "Ionizing radiation can cause BRCA1 to be exported to the cytoplasm from the nucleus, increasing the sensitivity of PARP inhibitors in the wild-type BRCA1 and homologous recombination proficient tumor cells." (PMID 35873570, 2022). "More and more tumor biomarkers, such as PD-L1, BRCA1/2, BRAF, HER2, etc., have been discovered, which become an indispensable tool in current tumor treatment due to its ability to assist various clinical decisions." (PMID 35668930, 2022). "We implanted CCNE1-amplified (HCC1569 and OVCAR3), BRCA1-mutated SUM149PT and BRCA- and CCNE1-normal A2780 cells to generate tumour xenografts in mice that were randomized to receive either RP-6306 or vehicle orally twice daily." (PMID 35444283, 2022). "We performed LOH analysis of tumor DNA from PT0198, the only available OC tumor DNA from BRCA1 c.5407-25T>A carriers." (PMID 35456503, 2022). "Yet, they had higher tumor mutation burden, and higher frequency of ATM and BRCA1 mutations (44% vs. 10%, p = 0.002 and 21% vs. 4%, p = 0.018, respectively)." (PMID 36362213, 2022). "BRCA1 is a major tumor suppressor that functions in the accurate repair of DNA double-strand breaks via homologous recombination (HR)." (PMID 35837282, 2022). "Previous studies have shown SAT1 promotes DNA double-strand break repair by regulating BRCA1 and homologous recombination, aiding in tumor survival." (PMID 36358597, 2022). "Tumours with BRCA1 or BRCA2 alterations were more sensitive to olaparib as compared to those with alterations in any other DDR gene." (PMID 36010882, 2022). "This also suggests that BRCA1 and BRCA2 mutation carriers should ideally be analyzed separately, due to their tumor’s biological differences." (PMID 35507134, 2022). "Key to their tumour suppressor activity, BRCA1 and BRCA2 are involved in homologous recombination, a high-fidelity repair pathway for DNA double-strand breaks." (PMID 35668475, 2022).
tumor (continued). "Immunostaining revealed that Tgfβr2 and p-Smad2 were highly expressed in p18−/−; Brca1MGKO tumor cells, and that the expression pattern of Tgfβr2 in p18−/−; Brca1MGKO tumors was similar with the pattern in p18−/−; Brca1+/− tumors." (PMID 35236825, 2022). "Among the ARGs in the risk model, BRCA1 and BRCA2 have been confirmed occurred mutation in TNBC, and were correlated with higher tumor grade and earlier age at menarche." (PMID 35297220, 2022). "In classical terms, BRCA1 fits the criteria of a candidate tumor suppressor gene and some of its archetypal biological activities are described in the next section." (PMID 35432218, 2022). "While BRCA1- and FANCJ-deficient tumor cells are both defective in HR, only BRCA1-deficient cells were sensitive to olaparib treatment, and this difference stemmed from distinct replication fork lengthening, which reflects replication-associated ssDNA gaps." (PMID 35163621, 2022). "In PC, BRCA1 co-regulates the AR activity mediating tumor progression, while BRCA2 limits the metastatic potential of PC by MMP9 downregulation and inhibition of the PI3K/AKT and MAP/ERK pathways (which also regulate PD-L1 expression)." (PMID 35203446, 2022). "Fails in detection in tumor samples (samples DNA_1-3; FFPE_1-3) corresponded to two frameshift mutations in BRCA2 (variants 2 and 6) and a splicing alteration in BRCA1 (variant 4)." (PMID 36579549, 2022). "Separate from the transcript analyses, the investigators described two patients with a BRCA1 germline PV and loss of heterozygosity (LOH) in GC tumor samples." (PMID 36497436, 2022). "HGSC is associated with lower prevalence but recurrent somatic mutations in NF1, BRCA1, BRCA2, RB1, and CDK12 in around 5–8% of tumours." (PMID 36531003, 2022). "The BRCA1 and BRCA2 tumour suppressor genes encode nuclear protein products that maintain genome integrity through various roles, including DNA repair, cell-cycle regulation and apoptosis." (PMID 35668475, 2022). "In an exploratory biomarker analysis in TOPARP-B, a RAD51 foci score as a surrogate measure of HRR function was able to identify all BRCA1/2-altered and PALB-2 biallelic loss tumours in keeping with HRR loss of function." (PMID 36497408, 2022). "Comparing two different BRCA1 mutations on N-terminal domain (185delAG and 5382insC) in genetically engineered mouse models, BRCA1 (185delAG) tumours responded significantly worse to PARPi than the BRCA1 (5382insC) tumours." (PMID 35681784, 2022). "Having shown that the levels of BRCA1/2 mRNAs were highly variable between tumor samples, we next analyzed the expression of the additional genes probed with the nCounter VantageTM RNA Panel for DNA Damage and Repair." (PMID 35203410, 2022). "The C-terminal BRCT region of BRCA1 is the receptor for 1JNX, which is required for DNA repair, tumor suppressor activities, and transcriptional regulation." (PMID 36676011, 2022). "Two germline PV/LPV were found in two patients, but were missed by tumor genotyping (one patient with BRCA1 large deletion and another patient with SNV in ATM)." (PMID 35326583, 2022). "Out of 641 patients analyzed, 56 (8.7%, 20 in BRCA1 and 36 in BRCA2) bore tumour BRCA PVs and 64 variants of uncertain significance (VUS)." (PMID 35463374, 2022). "Accordingly, as is characteristic of HR-deficient cells, MPB1 tumor cells isolated from EPO-GEMM tumors showed reduced induction of Rad51-containing nuclear foci following irradiation compared to MP tumor cells with intact Brca1." (PMID 35082152, 2022).
tumor (continued). "From the results of the tumor-associated genes analysis, the most significant ten tumor- associated genes such as SNAI2, VCAM, MMP2, BRCA1, PARP1 and MECOM were closely associated with UCPs." (PMID 35090503, 2022). "The interaction between RING domains within BARD1 and BRCA1 is critical for the tumour suppressive effects of the protein heterodimer, stimulating ubiquitin ligase activity." (PMID 33672422, 2021). "And the heatmap of the enriched genes in the pathways indicated that key genes involving tumor proliferation such as BRCA1, CDK1, and CCNB1 et, al." (PMID 35095481, 2021). "The tumour material from all of the 274 patients underwent sequencing for the BRCA1 and BRCA2 genes." (PMID 34680387, 2021). "BRCA1 expression hindered tumor development and sensitized these cells to chemotherapy, whereas its suppression promoted chemoresistance." (PMID 33777104, 2021). "Given the significance of BRCA1/2 gene integrity in HRR functionality, BRCA1/2 are often used as a metric for determining a tumor’s HRR status." (PMID 34711195, 2021). "DNA double-strand break repair by homologous recombination (HR) is one of the primary mechanisms by which BRCA1 acts as a tumor suppressor." (PMID 33888730, 2021). "To determine the prognostic role of BECN1 and BRCA1, we analyzed the survival of patients bearing a tumor with consistent CNV of the tumor suppressor genes, i.e., with both shallow deletion (240 cases) or diploid (50 cases) status." (PMID 33670664, 2021). "Furthermore, of the two treatment-naïve patients with somatic BRCA1 variants identified in FFPE tumor samples, we could detect in ctDNA a BRCA1 frameshift somatic variant that was present in the tumor sample with a VAF of 53%, but not the one that had a VAF of only 5.4%." (PMID 34660321, 2021). "Tumor testing was successful in 95% of samples (570/600) with at least one BRCA1/2 PV identified in 16% (93/570) of cases." (PMID 33030818, 2021). "The full-length BARD1 is classified as a tumour suppressor and the main partner of BRCA1 (forming a heterodimer via the RING domain)." (PMID 33530592, 2021). "While all germline BRCA1/2 PVs were identified in tumor at VAFs over 40% (VAF = 44–94%), confirmed germline VUS were seen at VAF in tumors as low as 5% and as high as 90%." (PMID 33030818, 2021). "Immune infiltrates in BRCA2 mutant tumors assume a potent anti-tumor phenotype, whereas myeloid cells infiltrating BRCA1 mutant tumors show immunosuppressive capacity." (PMID 34572943, 2021). "BRCA1/2-mutated, HR-deficient HGSOC is associated with increased neoantigens, tumor-infiltrating lymphocytes (TILs) and favorable prognosis than HR-proficient HGSOC." (PMID 33803939, 2021). "Strong Pdgfrβ expression ranged from 2 to 60% of p18−/−;Brca1+/− tumor cells, while Pdgfrβ expression was found in 2–5% of p18−/− tumor cells and was much weaker in intensity." (PMID 33478572, 2021). "The fact that both mammary and overall tumor development were most efficient in P2p53 mice also implies that PALB2 is at least as critical a tumor suppressor as BRCA1 and BRCA2." (PMID 33893322, 2021). "This cohort study examines the association of BRCA1 and BRCA2 with tumor mutation burden and response to immune checkpoint inhibitors." (PMID 33961040, 2021). "The clinical significance of OC-IS30 was tested in the external OV-TCGA dataset containing 312 HGSCs annotated in term of clinical and molecular finding (Stage, Overall Survival, mutational status of BRCA1 and BRCA2 genes, and tumor mutational burden (TMB)." (PMID 34220848, 2021).
tumor (continued). "We also confirmed that the positive effect of BRCA1+/− iMSCs on 4T1 tumor growth and dissemination is related to the increased development of tumor vessel networks, which promote lung metastasis." (PMID 33513753, 2021). "A large number of proteins are critical for HR, including the tumor suppressors BRCA1 and BRCA2, whose functions have been well characterized in somatic cells in the context of DNA damage and carcinogenesis." (PMID 33996823, 2021). "BRCA1 is a well-studied tumor suppressor involved in the homologous repair of DNA damage, whereas PINK1, a mitochondrial serine/threonine kinase, is known to be involved in mitochondrial quality control." (PMID 33888730, 2021). "The results were not appreciably different after adjustment for age at diagnosis, study, ethnicity, stage, grade, ER status, nodal status, and tumor size or when BRCA1/2 carriers were excluded." (PMID 34857041, 2021). "We demonstrated that reconstitution of Gata3 in Brca1-deficient tumor cells activates MET and eliminates potential for tumor initiation and metastasis." (PMID 34373738, 2021). "Of these, 11 (19%) patients had BRCA1/2-mutated tumors (7 BRCA1 and 4 BRCA2), 2 (4%) patients had tumors with BRIP1 mutations, and 1 (2%) patient had a tumor with a two-copy deletion of RAD51C." (PMID 34552099, 2021). "Specifically, BRCA1 is a tumor suppressor with an extensively documented role in DNA repair and homologous recombination (HR)." (PMID 34359660, 2021). "A total of 94 patients were referred for genetic counselling, including 48 patients with a tumour detected BRCA1/2 alteration." (PMID 34680387, 2021). "The tumour suppressor PALB2 mediates the physical interaction of BRCA2 with the COOH-terminal fragment of BRCA1." (PMID 34771713, 2021). "Retrospective studies have correlated BRCA1 and BRCA2 mutations, higher tumor mutation burden and infiltration by T cells with improved survival in HGSOC,36, 37 and BRCA2 mutations were found to be enriched among long‐term responders to PARP inhibition." (PMID 33811746, 2021). "In line with a potential anti-transformative effect of balanced ΔNp63 expression, this isoform has been described as a transcriptional target of BRCA1 and an important mediator of BRCA1-dependent tumor suppression." (PMID 34638302, 2021). "Intratumoral angiogenesis, as assessed by CD34 immunostaining of tumor sections, was found to be significantly increased in the BRCA1+/− iMSC treatment group." (PMID 33513753, 2021). "BRCA1-associated ring domain 1 (BARD1), nuclear partner of BRCA1, has been suggested as a potential HBOC risk gene, although its prevalence and penetrance are variable according to populations and type of tumor." (PMID 33498765, 2021). "RNF168 depletion led to a further increase of R-loop levels and reduced tumour formation in BRCA1-mutated cells, indicating a functional role of DHX9 ubiquitylation in R-loop resolution and tumour formation of BRCA1-deficient backgrounds." (PMID 33755171, 2021). "In an Italian prospective study comparing BRCA1/2 germline and tumor testing results from 62 patients with EOC, the concordance between tumor and germline BRCA tests was 87.1% (54 of 62), and the negative predictive value of the tumor test was 100%." (PMID 34202525, 2021). "Inherited mutations in the BRCA1 and BRCA2 genes as tumor suppressor lead to basal-like BC, and many TNBC with intact BRCA1/2 are classified as BRCAness lesions." (PMID 33804295, 2021). "The focus of PARP inhibitors (PARPis) to date has been on BRCA1 and BRCA2 mutated tumours, with clinical benefits seen in patients with mutations in these DNA repair genes such as ovarian, breast, prostate and pancreatic cancers." (PMID 34445211, 2021). "It has also been outlined by functional in vitro experiments that BRCA1-heterozygous cells create a proliferation-favoring environment compared to wild type adipose stromal cells, thus leading to tumor development enhancement." (PMID 33540843, 2021).